LOXL2 (lysyl oxidase like 2)
Diseases named in the same sentence as LOXL2 in open-access papers (continued):
Sharing a sentence is not in itself a finding about the gene and the disease.
glioma (13 papers, 2022 to 2025). A benign or malignant brain and spinal cord tumor that arises from glial cells (astrocytes, oligodendrocytes, ependymal cells). "Furthermore, the expression of LOX family members LOXL1 and LOXL2 in gliomas is also associated with tumor progression and poor prognosis." (PMID 40270974, 2025). "In this study, based on the mRNA-seq data of glioma patients from CGGA and TCGA databases, the expression levels of LOXL2 in different pathological types of gliomas were analyzed." (PMID 40756111, 2025). "LOXL2 overexpression correlated with higher glioma malignancy (P<0.001), particularly in IDH wild-type and 1p/19q non-codeleted subtypes (P<0.001)." (PMID 40756111, 2025). "Through the construction of nomogram and DCA model evaluation, the results indicate that LOXL2 has important translational value in the prognosis prediction of glioma." (PMID 40756111, 2025). "The time-dependent C-index was balanced around 0.7 at 500, 1000, 2000, 3000, and 4000 days, indicating that LOXL2 has important translational value in predicting the prognosis of glioma." (PMID 40756111, 2025). "In this study, we performed a comprehensive analysis of LOXL2 in glioma by using bioinformatics technology, including clinical samples and gene expression data from different countries." (PMID 40756111, 2025). "This study revealed that LOXL2 can be used as a potential biomarker in glioma and is correlated with clinical prognosis." (PMID 40756111, 2025). "Immune infiltration analysis showed that LOXL2 was closely related to macrophages, neutrophils and NK cells in glioma." (PMID 40756111, 2025). "Through functional enrichment analysis of the cross-dataset (CCGA and TCGA) of LOXL2 in glioma, we found that its core functions were significantly focused on extracellular matrix (ECM) dynamic remodeling and tumor invasion microenvironment regulation." (PMID 40756111, 2025). "With the in-depth study of the pathway of LOXL2, this molecule is expected to develop into a new therapeutic target and open up a new therapeutic approach for improving the clinical prognosis of glioma patients." (PMID 40756111, 2025). "This study focused on the key molecule LOXL2, which plays an important regulatory role in the pathological process of glioma." (PMID 40756111, 2025). "Loxl2 can activate glioma cell autophagy to induce the epithelial-to-mesenchymal transition (EMT) process and reduce chemotherapy sensitivity." (PMID 38978755, 2024). "Among these six genes, ANG, IL1A, LOXL1, LOXL2, and STEAP3 played risk roles in the survival of glioma patients (HR > 1), while F5 was a potential protective factor (HR < 1)." (PMID 37891828, 2023). "Respectively, which proved that LOXL2 could be used as an independent prognostic indicator for glioma." (PMID 40756111, 2025). "For glioma Lysine Oxidase 2(LOXL2), there are few reports in the scholarly literature." (PMID 40756111, 2025). "Through immune infiltration analysis, we found that LOXL2 may regulate the immune function of glioma through the cooperation of macrophages and neutrophils." (PMID 40756111, 2025). "In summary, this study comprehensively analyzed the potential of LOXL2 as a glioma biomarker." (PMID 40756111, 2025). "Furthermore, our analysis uncovered a distinct LOXL2-overexpressing malignant cell population in recurrent glioma, characterized by activation of collagen, laminin, and semaphorin-3 pathways, along with enhanced epithelial-mesenchymal transition." (PMID 40186284, 2025). "Previous studies in glioma indicated the independent prognostic role of Loxl2." (PMID 38978755, 2024). "LOXL2 expression indicated poor overall survival of glioma patients, and LOXL2 may serve as a promising therapeutic target in the treatment of glioma." (PMID 37142620, 2023). "In glioma, LOXL2 upregulation would trigger EMT through the induction of autophagy." (PMID 36830091, 2023).
glioma (continued). "Especially in glioma, the expression intensity of LOXL2 is significantly correlated with the clinical outcome of patients, and its mechanism of action may involve biological processes such as tumor microenvironment remodeling and immune cell infiltration regulation." (PMID 40756111, 2025). "However, there are few relevant literatures on LOXL2 in glioma." (PMID 40756111, 2025). "At the molecular function (MF) level, LOXL2 specifically binds to collagen and integrin, and endows the ECM with tensile strength, providing a mechanical shelter microenvironment for glioma stem cells." (PMID 40756111, 2025). "The results indicated that members of the LOX family, including LOX, LOXL1, LOXL2, LOXL3, and LOXL4, exhibited high expression levels in glioma cells in comparison to normal human glial cell lines Heb as well as glioblastoma cell lines T98G and LN-229." (PMID 40270974, 2025). "LOXL2 and LOXL3, members of the lysyl oxidase (LOX) family, LOXL2 was found to promote glioma progression, and improve the TMZ resistance of glioma cells." (PMID 36856182, 2023). "The experimental results in our present work demonstrated the elevations of LOX, LOXL1, LOXL2, and LOXL3 in various glioma cell lines." (PMID 36160460, 2022). "Experimental results revealed that expressions of LOX, LOXL1, LOXL2, and LOXL3 were higher in glioma cell lines at mRNA and protein levels." (PMID 36160460, 2022). "This analysis revealed that high expression of LOXL2 was strongly correlated with advanced pathological characteristics of glioma, IDH wild type and 1p/19q non-codeletion, suggesting its potential value as a biomarker for malignant progression of glioma." (PMID 40756111, 2025). "KEGG pathway analysis further revealed that LOXL2 may activate the FAK/PI3K-Akt signaling axis through ECM-receptor interaction, suggesting its potential role in glioma immune escape." (PMID 40756111, 2025). "The results shown in CGGA-325 dataset revealed that the glioma patients with the high levels of all members of LOX family including LOX, LOXL1, LOXL2, LOXL3, and LOXL4 displayed poor prognosis with the MST of only 34.3, 31, 31, 35.3, and 34.8 months, respectively." (PMID 36160460, 2022). "Finally, RT-qPCR and Western blot analysis were carried out to validate the mRNA and protein levels of LOXs including LOX, LOXL1, LOXL2, LOXL3, and LOXL4 in glioma cells (T98G and A172) and the normal cell line (HEB)." (PMID 36160460, 2022). "The results indicated that the mRNA and protein expressions of LOX, LOXL1, LOXL2, and LOXL3 were significantly upregulated in these glioma cells than in HEB cell line while the expressions of LOXL4 at mRNA and protein level were not determined in these cell lines (data not shown)." (PMID 36160460, 2022). "Additionally, experimental results also revealed that expressions of LOX, LOXL1, LOXL2, and LOXL3 were higher in glioma cell lines (T98G and A172) at mRNA and protein levels compared with the normal astrocyte HEB." (PMID 36160460, 2022). "Previous studies have shown that LOXL2, a member of the lysyl oxidase (LOX) family, not only promotes glioma cell proliferation, migration, and invasion and induces the epithelial-to-mesenchymal transition (EMT) process but also reduces the sensitivity of glioma cells to temozolomide (TMZ)." (PMID 36588901, 2022).
prostate carcinoma (13 papers, 2016 to 2025). A carcinoma that arises from epithelial cells of the prostate gland. "LOXL2 expression is up-regulated in prostate cancer compared with normal tissue and is associated with poor prognosis in a variety of cancers." (PMID 31061140, 2019). "Although LOXL2 has been implicated in the progression of multiple solid tumors and is overexpressed in prostate cancer, few studies have reported a specific role for LOXL2 in prostate CAF function." (PMID 31061140, 2019). "In prostate cancer cells, elevated levels of LOXL-2 have been detected, supporting the possible involvement of this protein in the effects of the JNK pathway on the prostatic carcinogenesis." (PMID 33800291, 2021). "In the present study, we investigated differences in the expression of LOXL2 between androgen-dependent and -independent prostate cancer cell lines and the regulating effect of LOXL2 on the radiosensitivity of CRPC cells." (PMID 30809541, 2019). "By data mining of high-throughput microarray data of prostate cancer cell lines deposited in the GEO database, LOXL2 was found to be significantly upregulated in all three CRPC cell lines as compared with the androgen-dependent prostate cancer cell lines." (PMID 30809541, 2019). "The effect of LOXL2 knockdown on the radiosensitivity of androgen-independent prostate cancer cells lines was measured by the clonogenic assay and xenograft tumor experiments under in vitro and in vivo conditions, respectively." (PMID 30809541, 2019). "To demonstrate clinical relevance of LOXL2 we interrogated the prostate cancer RNA-seq data set (n = 492) of The Cancer Genome Atlas (TCGA) for LOXL2 gene expression levels in patients with localized prostate cancer." (PMID 31061140, 2019). "By using bioinformatic data mining methods, LOXL2 was found to be upregulated in both androgen-independent prostate cancer cell lines and radioresistant tumor samples collected from patients with prostate cancer." (PMID 30809541, 2019). "A recent report claimed that miR-29c together with other five miRNAs such as miR-29a, miR-29b, miR-26a, miR-26b and miR-218 can control the expression of metastasis-promoting LOXL2 gene during the development of prostate cancer." (PMID 28340554, 2017). "It was previously shown that CAF-derived LOXL2 plays an important role in intercellular communication in the prostate tumor microenvironment and could be used to treat prostate cancer." (PMID 36937411, 2023). "LOXL2 knockdown by shRNA in castration-resistant prostate cancer cells." (PMID 34900673, 2021). "It is evident that dysregulation of the DDR2-collagen-LOXL2 axis in early prostate cancer would therefore provide a potent and pro-tumorigenic microenvironment, capable of driving aggressive disease and that this axis can be targeted with therapeutic interventions." (PMID 31061140, 2019). "However, a rare study that focused on the role of LOXL2 in prostate cancer is available." (PMID 30809541, 2019). "On the other hand, Lysyl oxidase-like 2 (LOXL2), a protein that induces EMT, is involved in radiotherapy resistance in prostate cancer cells and in xenografts mice model." (PMID 34003341, 2021). "In summary, we determined that LOXL2 was upregulated in both CRPC cell lines and RR prostate cancer samples by a bioinformatic approach and confirmed this with our own real-time quantitative PCR data." (PMID 30809541, 2019). "The functional role of LOXL2 in regulating ECM organization and migration of both CAF and co-cultured prostate cancer cells was validated with LOXL2 inhibitors." (PMID 31061140, 2019). "Within the intersection DEGs of the two datasets, we observed that LOXL2 was consistently upregulated in CRPC cell lines, as determined in the GEO dataset, and radioresistant prostate cancer samples, as determined in the TCGA dataset." (PMID 30809541, 2019).
colon cancer (12 papers, 2009 to 2024). "CAFs also stimulate EMT in colon cancer LOVO cells to promotes colon cancer metastasis through activating the focal adhesion kinase (FAK) signaling pathway by secreting LOXL2." (PMID 39139454, 2024). "When colon cancer patient-derived CAFs and normal fibroblasts were compared by proteomic analysis, LOXL2 was found to be overexpressed in CAFs and was identified as a predictive prognostic factor in stage II colon cancer patients." (PMID 31106200, 2019). "For example, expression of Lysyl oxidase-like 2 protein in Snail1- positive tumour cells may modulate the effects of Snail1 in colon tumour cells, as it has been demonstrated in a recent study with squamous cell carcinomas." (PMID 19440385, 2009). "In Xue’s study, LOXL2 secreted by CAFs activated the FAK signaling pathway and then induced EMT in human colon cancer LOVO cells, thereby promoting the invasion and metastasis of colon cancer." (PMID 34930321, 2021). "This in turn increases matrix stiffness and cancer cell invasion and it has been found that lysyl oxidase-like 2 (LOXL2) is overexpressed in CAFs of CRC, which could be used as a marker for predicting the prognosis of colon cancer patients." (PMID 39139454, 2024). "A subset of ECM glycoproteins, such as thrombospondin-2 (THBS2), ECM regulators including lysyl oxidase homolog 2 (LOXL2) or procollagen-lysine,2-oxoglutarate 5-dioxygenase 1 (PLOD1), and affiliated proteins such as MUC13 have been specifically identified in colon cancer samples." (PMID 33297478, 2020). "Likewise, high LOXL2 mRNA expression has been found to associate with lymph node metastasis in esophageal squamous cell carcinoma and with decreased overall survival in lung squamous cell carcinoma and lymph node-negative breast adenocarcinoma, and in colon cancer." (PMID 30701028, 2018).
colorectal cancer (12 papers, 2017 to 2026). A primary or metastatic malignant neoplasm that affects the colon or rectum. "Taken together, NID1 is a pivotal downstream gene of ETV4/LOXL2 promoting aggressive phenotype in colorectal cancer." (PMID 41281746, 2025). "Collectively, our data determined that LOXL2 indeed plays a role in promoting colorectal cancer cells growth and invasion." (PMID 41281746, 2025). "On the other hand, high levels of LOXL2 inhibit the 5-FU-induced apoptosis of colorectal cancer cells." (PMID 37762708, 2023). "LOXL2 expression is increased in a number of tumor types, including colorectal cancer where it is also a marker for poor prognosis." (PMID 30473751, 2018). "To identify the molecular mechanism underlying the ETV4-mediated EMT and metastasis in colorectal cancer cells, we next leveraged our RNA-seq data and a series of key downstream genes associated with EMT were further confirmed, including MER3, MSX1, LOXL2, THRB, WISP2, COL11A1, ADRB2 and E2F2." (PMID 41281746, 2025). "Consistently, LOXL2 knockdown could markedly inhibit the proliferation of ETV4-overexpression colorectal cancer cells, as evidenced by colony formation assays." (PMID 41281746, 2025). "In colorectal cancer cells, LINC01347 enhances LOXL2 expression by competing with miR-328, resulting in an increase in cell proliferation and chemotherapy resistance." (PMID 37762708, 2023). "We next to verify whether ETV4/LOXL2/NID1 induce EMT transformation and metastasis in colorectal cancer cells by activating ERK signaling pathway." (PMID 41281746, 2025).
esophageal squamous cell carcinoma (11 papers, 2014 to 2025). Esophageal squamous cell carcinoma (ESCC) is a type of esophageal carcinoma (EC) that can affect any part of the esophagus, but is usually located in the upper or middle third. "In our previous study, LOXL2 was found to be overexpressed in esophageal squamous cell carcinoma (ESCC) cell lines and clinical samples and was significantly associated with lymph node metastasis." (PMID 25254241, 2014). "LOXL2 (lysyl oxidase-like 2), an enzyme that catalyzes oxidative deamination of lysine residue, is upregulated in esophageal squamous cell carcinoma (ESCC)." (PMID 25254241, 2014). "LOXL2 was shown to promote esophageal squamous cell carcinoma (ESCC) migration and invasion." (PMID 36232685, 2022). "The LCN2/LOXL2/MMP9 ternary complex promoted migration and invasion of oesophageal squamous cell carcinoma (ESCC) cells, as well as tumour growth and malignant progression in vivo, while the iron chelator deferoxamine mesylate (DFOM) inhibited ESCC tumour growth." (PMID 37753805, 2023).
melanoma (11 papers, 2018 to 2025). A malignant, usually aggressive tumor composed of atypical, neoplastic melanocytes. "Further, we compared the Kaplan–Meier survival curves of patients with primary melanomas displaying low and high expression of LOXL2 and found a significant association between high expression of LOXL2 and shorter survival time." (PMID 30701028, 2018). "Further, LOXL2 was significantly upregulated in clinical human primary melanomas compared to benign nevi, and high expression of LOXL2 in primary melanomas was associated with formation of metastases and shorter survival of patients." (PMID 30701028, 2018). "LOXL2 proved to be the most interesting among the LOX family members in melanomas, as it was significantly upregulated in clinical human melanomas compared to benign nevi, and it was associated with the formation of metastases and shorter survival of patients." (PMID 30701028, 2018). "As we had earlier incidentally noticed by microarray analysis two melanoma cell lines to overexpress LOXL2, we additionally studied the expression levels of all LOX family genes in different melanoma cell lines." (PMID 30701028, 2018). "To resolve this paradox, we further studied the functions of the encoded proteins by using a universal LOX inhibitor Β-aminopropionitrile (BAPN) and knocking down of LOX and LOXL2 in melanoma cells." (PMID 30701028, 2018). "Knocking down the expression of LOX and especially LOXL2 in melanoma cells almost completely abrogated the invasive growth capability." (PMID 30701028, 2018). "Interestingly, our studies revealed that the depletion of LOX, and particularly that of LOXL2 by shRNAs inhibited both the proliferative capacity and the invasive growth capability of melanoma cells much more effectively than BAPN." (PMID 30701028, 2018). "LOXL2 may also serve as a prognostic factor in melanoma as we found high LOXL2 mRNA expression in primary melanomas to be associated with formation of metastases and shorter survival of patients." (PMID 30701028, 2018). "Our data suggest that inactive pro-LOX functions as a tumor suppressor in ODC- and RAS-transformed mouse fibroblasts by inhibiting cell growth and invasion, and that the mature, active LOX and LOXL2 act as tumor promoters in human melanoma cells by promoting their invasive growth." (PMID 30701028, 2018). "Further, we show that high LOXL2 mRNA expression may be correlated with metastasis and poor survival in melanoma." (PMID 30701028, 2018). "Thus, our studies reveal that inactive pro-LOX (together with Lox propeptide) functions as a tumor suppressor in ODC- and RAS-transformed murine fibroblasts by inhibiting cell growth and invasion, and active LOX and LOXL2 as tumor promoters in human melanoma cells by promoting their invasive growth." (PMID 30701028, 2018). "In addition to cell lines, we also compared the mRNA expression levels of LOX and LOXL1-4 in clinical tissue specimens of human benign nevi and malignant melanomas, and found LOXL1 (fold 1.6; p = 0.0028) and LOXL2 (fold 2.0; p = 0.00016) to be significantly upregulated in the primary melanomas." (PMID 30701028, 2018). "The cellular and secreted protein levels of LOX and LOXL2 in fibroblasts (HES) and melanoma cells (SK-MEL-147, WM793 and WM239) were then studied." (PMID 30701028, 2018). "The protein expression of LOXL2, in turn, was abundant in both HES and the melanoma cells, and varied less than that of LOX, with SK-MEL-147 showing the lowest expression." (PMID 30701028, 2018). "A mouse model of human melanoma was established on the basis of the A375 cell line, for which the expression of the oncologically relevant lysyl oxidase isoforms LOX and LOXL2 was demonstrated in Western blot and immunohistochemical experiments." (PMID 29755969, 2018). "We further show that the invasive growth of melanoma cells can be inhibited with ΒAPN, and even totally blocked by depletion of LOX and LOXL2 with shRNAs." (PMID 30701028, 2018).